CUBN (cubilin)
Description:
Endocytic receptor which plays a role in lipoprotein, vitamin and iron metabolism by facilitating their uptake. Acts together with LRP2 to mediate endocytosis of high-density lipoproteins, GC, hemoglobin, ALB, TF and SCGB1A1. Acts together with AMN to mediate endocytosis of the CBLIF-cobalamin complex. Binds to ALB, MB, Kappa and lambda-light chains, TF, hemoglobin, GC, SCGB1A1, APOA1, high density lipoprotein, and the CBLIF-cobalamin complex. Ligand binding requires calcium. Serves as important transporter in several absorptive epithelia, including intestine, renal proximal tubules and embryonic yolk sac. May play an important role in the development of the peri-implantation embryo through internalization of APOA1 and cholesterol. Binds to LGALS3 at the maternal-fetal interface.
Synonyms: IFCR; gp280; IGS; IGS1; MGA1
Tractability: Small molecule: a structure with a bound ligand is known. Antibody: UniProt places it where antibodies can reach, with high confidence; its Gene Ontology location is reachable by antibodies, with high confidence; UniProt predicts a signal peptide or a membrane-spanning region.
Gene: Protein-coding gene on chromosome 10 (16,823,966 to 17,129,811, reverse strand). Ensembl gene ENSG00000107611.
Subcellular location: Apical cell membrane; Cell membrane; Membrane, coated pit; Endosome; Lysosome membrane
Pathways (Reactome):
Disease: Defective AMN causes MGA1; Defective CUBN causes MGA1
Metabolism: Uptake of dietary cobalamins into enterocytes; Vitamin D (calciferol) metabolism
Transport of small molecules: HDL clearance
Gene Ontology:
Molecular function: cargo receptor activity; protein binding; protein homodimerization activity; signaling receptor activity; calcium ion binding
Biological process: cobalamin metabolic process; cobalamin transport; receptor-mediated endocytosis; tissue homeostasis; vitamin D metabolic process
Cellular component: apical plasma membrane; endocytic vesicle; endosome; extracellular exosome; membrane; microvillus membrane; plasma membrane; receptor complex; brush border membrane; cytosol; extrinsic component of external side of plasma membrane; lysosomal lumen; lysosomal membrane; apical part of cell; brush border; cell projection membrane; clathrin-coated pit; cytoplasm; endoplasmic reticulum; Golgi apparatus
Genetic constraint (gnomAD): Loss-of-function variants: 263 observed, 385.13 expected, observed/expected ratio (o/e) 0.68, 90% interval 0.62 to 0.76. The upper end of that interval is the gene's LOEUF score, 0.76, which puts it in group 3 of 6, group 1 being the genes least tolerant of losing a copy. Missense variants: 4,358 observed, 4,542.7 expected, observed/expected ratio (o/e) 0.96, 90% interval 0.94 to 0.98. Synonymous variants: 1,638 observed, 1,656 expected, observed/expected ratio (o/e) 0.99, 90% interval 0.95 to 1.03.
Homologues: Orthologues: chimpanzee CUBN (99% identical), macaque CUBN (95% identical), dog CUBN (83% identical), pig CUBN (80% identical), rabbit CUBN (78% identical), guinea pig CUBN (74% identical), rat Cubn (70% identical), mouse Cubn (70% identical), tropical clawed frog cubn (56% identical), zebrafish cubn (53% identical), Drosophila melanogaster Cubn2 (24% identical), Drosophila melanogaster tok (10% identical). Paralogues in human: CNTNAP3 (6% identical), CNTNAP3B (6% identical), CNTNAP4 (6% identical), CNTNAP5 (6% identical), CNTNAP2 (6% identical), F8 (5% identical), CNTNAP1 (5% identical), TLL1 (5% identical), F5 (5% identical), BMP1 (5% identical), NRXN2 (5% identical), NRXN1 (5% identical), and 23 more.
Diseases named in the same sentence as CUBN in open-access papers:
CUBN is named in the same sentence as 101 diseases in open-access papers, as found by Europe PMC text mining. Sharing a sentence is not in itself a finding about the gene and the disease. The quoted sentences say what the papers report.
diabetes (16 papers, 2011 to 2025). "Although we demonstrate that C-terminal missense variants in CUBN are associated with different measures of normal (or even higher) kidney function in non-diabetes, we emphasize that the current study is insufficient to establish causality." (PMID 36926036, 2023). "Boger et.al found a missense mutation (I2984V) of CUBN gene which is associated with albuminuria in general population and in individuals with diabetes." (PMID 34979989, 2022). "The CUBN allele effects on ACR were twice as strong in people with diabetes—a result robust to an optimization-algorithm approach to simulating interactions, validating previously reported gene–diabetes interactions (P ≤ 4 × 10–5)." (PMID 31630189, 2019). "The minor alleles at the low-frequency and rare CUBN variants also showed evidence of statistical interaction with diabetes status, with larger effects on ACR in people with diabetes (rs45551835 Pinteraction = 6 × 10−7; rs141640975 Pinteraction = 4 × 10−5)." (PMID 31630189, 2019). "Rare genetic variants in the CUBN gene encoding the main albumin-transporter in the proximal tubule of the kidneys have previously been associated with microalbuminuria and higher urine albumin levels, also in diabetes." (PMID 36926036, 2023). "We performed interaction analyses to test whether the 62 lead variants had stronger effects in individuals with diabetes as previously observed for the CUBN locus." (PMID 31630189, 2019). "A strong interaction between diabetes status and CUBN missense rs141640975 observed with respect to albuminuria in the current study suggests potential clinical implications." (PMID 30547231, 2019). "When combining variants into a weighted GRS (excluding CUBN variants), we observed evidence of interaction with diabetes status, with the GRS having larger effects in people with diabetes (Pinteraction = 2 × 10−6)." (PMID 31630189, 2019). "We replicated the statistical interactions between the common and rare CUBN signals and diabetes status." (PMID 31630189, 2019). "Patients with T1D who have developed MA in the EDC (The Pittsburgh Epidemiology of Diabetes Complications) study demonstrated urinary cubilin shedding prior to development of MA." (PMID 26465605, 2015). "The positive associations between the four CUBN missense variants and eGFR in a large population without diabetes suggests a pleiotropic role of CUBN as a novel eGFR-locus in addition to it being a known albuminuria-locus." (PMID 36926036, 2023). "For all four CUBN variants, we report significantly higher eGFRcreatinine-levels in individuals without diabetes harboring more copies of the minor alleles compared to individuals with fewer or no copies of the minor alleles in the same group." (PMID 36926036, 2023). "Therefore, we investigated the relationship between the four CUBN variants and eGFR in different contexts: First, we meta-analyzed studies of SNV-eGFRcreatinine regressions in Europeans with type 1 (T1D) or type 2 diabetes mellitus (T2D)." (PMID 36926036, 2023). "The current study identifies a rare coding variant in the CUBN locus and other potential genes associated with albuminuria in individuals with and without diabetes." (PMID 30547231, 2019). "Furthermore, we found that diabetes dramatically induced kidney injury molecule 1 (Kim-1), a marker for proximal tubular injury, and downregulated cubilin, a receptor for albumin uptake." (PMID 26398934, 2015). "Our results showed that diabetes markedly upregulated Kim-1 and downregulated cubilin." (PMID 26398934, 2015). "Finally, the effect of the rs10795433 variant in the CUBN locus—the major locus for albuminuria—was larger among individuals with diabetes compared to those without diabetes." (PMID 37324271, 2023).
diabetes (continued). "Additionally, a post hoc analysis of data from the Diabetes Control and Complications Trial (DCCT) and Epidemiology of Diabetes Interventions and Complications (EDIC) study also confirmed an association between CUBN mutations and an increased risk of developing microalbuminuria." (PMID 32681438, 2021). "The rare CUBN variant had an effect that was three times stronger in individuals with type 2 diabetes compared with those without (pinteraction = 7.0 × 10−4, β with diabetes = 0.69, β without diabetes = 0.20) in the discovery meta-analysis." (PMID 30547231, 2019). "We also speculated whether the apparent lack of association between CUBN and eGFR in our diabetes meta-analysis could be due to use of Angiotensin receptor blockers (ARBs) or Angiotensin-converting enzyme inhibitor (ACEi) medication which is frequently used in diabetes treatment." (PMID 36926036, 2023). "Index SNPs at CUBN and HPN (Hepsin) showed larger effect sizes among those with diabetes compared with the overall sample." (PMID 31511532, 2019). "In conclusion, the current study identifies the existence of pleiotropic genetic effects of CUBN on two facets of kidney function – albuminuria and eGFR – by reporting SNV-eGFR associations in a large study population without diabetes." (PMID 36926036, 2023). "Associations of the three statistically independent SNPs at the CUBN locus within individuals with diabetes and without diabetes." (PMID 31630189, 2019). "Although CUBN is a known locus for albuminuria, the identified rare missense variant shows independent effects (with respect to known SNPs in CUBN) that are stronger within the diabetes vs the non-diabetes group (pinteraction = 7.0 × 10−4)." (PMID 30547231, 2019). "The effect estimates of CUBN rs141640975 were more than threefold higher in the type 2 diabetes group (β = 0.69; p = 2.0 × 10−5) in comparison with the non-diabetes group (β = 0.20; p = 0.002) with a significant interaction based on diabetes status (pinteraction = 7.0 × 10−4)." (PMID 30547231, 2019). "Recently, we and others identified that genetic variants (single nucleotide variants (SNVs)) in the gene encoding for cubilin (CUBN) – the main albumin-transporter in PTCs – are associated with microalbuminuria and higher urine albumin levels in populations with and without diabetes." (PMID 36926036, 2023).
Imerslund-Gräsbeck syndrome (15 papers, 2012 to 2025). "Mutations in CUBN lead to Imerslund-Gräsbeck syndrome (IGS), a disorder characterized by vitamin B12 deficiency (and consequences related to that) with or without albuminuria." (PMID 39911140, 2025). "Biallelic CUBN variants cause Imerslund-Gräsbeck syndrome (IGS), often accompanied by proteinuria, whereas C-terminal variants have been associated with autosomal recessive chronic benign proteinuria." (PMID 41624452, 2025). "Imerslund-Gräsbeck Syndrome (IGS) is a rare autosomal recessive disease caused by mutations of CUBN or AMN gene." (PMID 34979989, 2022). "Biallelic pathogenic variants in CUBN gene, coding for cubilin, cause Imerslund-Gräsbeck Syndrome characterized by megaloblastic anemia and variable proteinuria." (PMID 33530161, 2021). "This represents the third cubilin variant causing inherited selective cobalamin malabsorption in a large animal ortholog of human Imerslund-Gräsbeck syndrome." (PMID 30591068, 2018). "Mutations in either the AMN or CUBN genes lead to Imerslund-Gräsbeck syndrome (IGS) or selective cobalamin malabsorption." (PMID 23613799, 2013). "Recessive mutations in CUBN or AMN cause Imerslund-Gräsbeck Syndrome (IGS), while recessive mutations in GIF cause Intrinsic Factor Deficiency (IFD)." (PMID 22929189, 2012). "In addition to Imerslund-Gräsbeck Syndrome, CUBN gene mutations have been reported in only a few cases with isolated proteinuria." (PMID 34979989, 2022). "Imerslund-Gräsbeck Syndrome (IGS) is mainly caused by CUBN gene biallelic mutations." (PMID 34979989, 2022). "Additionally, patients with Imerslund-Gräsbeck syndrome, caused by a mutation in the cubilin gene, in general suffer from proteinurea, demonstrating the importance of cubilin in protein renal reabsorption." (PMID 25161624, 2014). "Using targeted Sanger sequencing of AMN and CUBN, we identified novel compound heterozygous mutations in AMN in a family from the United Kingdom with typical clinical features of Imerslund-Gräsbeck Syndrome." (PMID 26040326, 2015). "In humans and dogs various gene variants in both CUBN and AMN are found causing hereditary selective intestinal cobalamin malabsorption with mid- to low-molecular weight proteinuria, an autosomal recessive trait also known as Imerslund-Gräsbeck syndrome (I-GS)." (PMID 30591068, 2018). "We aimed to investigate whether common variation, as opposed to rare mutations in Imerslund-Gräsbeck syndrome, in the CUBN associates with kidney disease." (PMID 22574174, 2012).
Nephropathy (14 papers, 2012 to 2024). A nonspecific term referring to disease or damage of the kidneys. "Until now, focal segmental glomerulosclerosis has just been reported in 1 of 4 patients in genetic kidney disease cohort II with CUBN gene mutations." (PMID 34979989, 2022). "Consequently, glycan alterations are found in many diseases and multiple studies have identified mutations in megalin and cubilin associated with kidney disease and proteinuria." (PMID 35970386, 2022). "In 2011, Ovunc et.al identified a homozygous frameshift mutation in CUBN gene in two siblings of consanguineous patients with intermittent nephrotic-range proteinuria, which indicated that cubilin mutation may be considered as a rare single-gene cause of nephropathy." (PMID 34979989, 2022). "Our results show that cubilin glycosylation can impede albumin interaction thus potentially contributing to albuminuria observed in kidney disease." (PMID 35970386, 2022). "Since megalin and cubilin PTC expression is altered in DD1, it is conceivable that LRP2 and/or CUBN mutations can cause or contribute to a DD-like nephropathy." (PMID 31947599, 2020). "Evidence suggests that megalin and the cubilin-amnionless complex are involved in the uptake of toxic substances into PTECs, which leads to the development of kidney disease." (PMID 25019425, 2014). "In light of findings presented herein, it is possible that drugs that inhibit HDACs might ameliorate renal disease by releasing epigenetic suppression of PPARs, cubilin and megalin." (PMID 23773363, 2013). "This is the second reported family with isolated proteinuria due to biallelic CUBN variants in the absence of megaloblastic anaemia, demonstrating the ability of genomic testing to identify genetic causes of nephropathy within expanding associated phenotypic spectra." (PMID 31438875, 2019). "First, the clinical relevance of genes detected in our screen, CUBN and COL4A4, is underscored by a respective monogenic disease featuring albuminuria and kidney disease, Imerslund-Grasbeck (MIM 261100) and Alport syndrome (MIM 203780)." (PMID 31511532, 2019). "CUBN-rs1801239 and DDR1-rs116772905 were associated with all the UACR-derived phenotypes, in both the overall and non-diabetic cohorts, but not with kidney damage." (PMID 37446387, 2023). "CUBN-rs1801239 and DDR1-rs116772905 were associated with all the UACR-derived phenotypes, (along with SHROOM3-rs17319721 and ALLC-rs12615970, except for macroalbuminuria) at least in the overall and non-diabetic cohorts, but not with kidney damage." (PMID 37446387, 2023). "Additionally, in vivo experiments further confirmed that the reduced expression of renal Cubilin did not cause abnormal cytoplasmic localization of AMN in the mice model of LPS-induced acute kidney injury and Adriamycin-induced nephropathy with GFB impairment." (PMID 36266725, 2022).
megaloblastic anemia (13 papers, 2006 to 2025). Anemia characterized by the presence of unusually large erythroblasts in the bone marrow called megaloblasts. "CUBN, which encodes cubilin, was originally identified as the causative gene of Imerslund–Gräsbeck syndrome, a disorder of megaloblastic anemia associated with proteinuria." (PMID 40163114, 2025). "The spectrum of clinical presentations associated with CUBN pathogenic variants ranges from megaloblastic anemia type 1 (IGS) to isolated benign proteinuria." (PMID 37312928, 2023). "Due to the combination of megaloblastic anemia, vitB12 deficiency and proteinuria, screening for abnormalities in the AMN and CUBN gene was performed." (PMID 37710296, 2023). "CUBN and AMN mutations were originally described in patients with Imerslund–Gräsbeck syndrome which is characterized by megaloblastic anemia and proteinuria." (PMID 29594119, 2018). "IGS, a rare autosomal recessive disorder caused by mutations in cubilin (CUBN) and/or amnionless (AMN), was first characterized in the 1960s and results in megaloblastic anemia during childhood as a result of selective malabsorption of Vitamin B12." (PMID 25147783, 2014). "For this patient, the variants in CUBN are downstream of IF-B12 binding domain; consequently, this patient did not exhibit vitamin B12 deficiency or megaloblastic anemia." (PMID 39911140, 2025). "Cubilin(encoded by CUBN), amnionless(encoded by AMN), and megalin form a multiligand receptor complex; CUBN or AMN gene variants have been implicated as a hereditary cause of megaloblastic anemia, proteinuria, and neurological impairment." (PMID 38992620, 2024). "Previous studies have demonstrated that CUBN gene mutations can cause IGS that typically manifests as megaloblastic anemia and secondary neurological symptoms, with or without proteinuria." (PMID 34979989, 2022). "CUBN mutations were also described in patients with intermittent nephrotic-range proteinuria without megaloblastic anemia." (PMID 29594119, 2018). "CUBN gene mutation may cause Imerslund–Grasbeck syndrome (OMIM 261100), which is a rare autosomal recessive disease characterized by vitamin B12 malabsorption resulting in megaloblastic anemia and asymptomatic proteinuria." (PMID 36583005, 2022). "Biallelic CUBN variants can cause isolated proteinuria without the megaloblastic anemia seen in IGS, which is termed PROCHOB (OMIM: 618884)." (PMID 40163114, 2025). "Defects in cubilin were previously only known to result in an autosomal recessive condition called Imerslund–Gräsbeck syndrome (IGS), which is characterized by intestinal vitamin B12 malabsorption, megaloblastic anemia, and, in half of cases, proteinuria." (PMID 37312928, 2023).
vitamin B12 deficiency (10 papers, 2012 to 2025). A disease characterized by low serum levels of vitamin B12, either inherited or acquired. "Metformin has effect on the cubilin, which in turn, affects intrinsic factor-vitamin B12 complex absorption causing vitamin B12 deficiency." (PMID 36584077, 2022). "Breed-specific cubam mutations that cause life-threatening cobalamin deficiency in dogs now include a CUBN splice-site variant (CUBN c.NM_001003148.1; c.8746 + 1G > A) segregating among Komondors." (PMID 30591068, 2018). "Variants in CUBN, the gene encoding cubilin, a proximal tubular transport protein, have been associated with albuminuria and vitamin B12 (B12) deficiency." (PMID 25644490, 2015). "Decreased expression of Cubilin was observed in the intestine of 21-month-old mice, which might contribute to aging-induced vitamin B12 deficiency." (PMID 22929163, 2012). "Overexpression of the cobalamin receptor subunits amnionless (AMN) and cubilin (CUBN) in the ileum was detected and presumed to be a mechanism to compensate for CIE-associated hypocobalaminemia." (PMID 36213409, 2022). "Third, the location of CUBN variants dictates phenotypic consequences, with C-terminal variants leading to albuminuria without vitamin B12 deficiency." (PMID 39911140, 2025).